PDK1 (pyruvate dehydrogenase kinase 1)
Diseases named in the same sentence as PDK1 in open-access papers (continued):
Sharing a sentence is not in itself a finding about the gene and the disease.
prion disease (5 papers, 2015 to 2024). A transmissible disease that is caused by a protein that is able to induce abnormal folding of normal cellular proteins, leading to characteristic spongiform brain changes, which are associated with neuronal loss without an inflammatory response. "We recently reported that accumulation of PrPSc in prion diseases relates to internalization of TACE α-secretase in caveolin-1 (Cav-1)-enriched microvesicles caused by PDK1 overactivation, which cancels PrPC neuroprotective α-cleavage by TACE." (PMID 26241960, 2015). "The final study in this section looks at the enzyme 3-Phosphoinositide-dependent protein kinase-1 (PDK1), both in AD and prion disease." (PMID 34489620, 2021). "In 2013, our laboratory provided prime evidence that the corruption of PrPC coupling to 3-phosphoinositide-dependent kinase 1 (PDK1) and downstream TACE α-secretase plays a critical role in the neuropathogenesis of prion diseases." (PMID 39011540, 2024). "Here, using mice, the authors show that prion infection enhances Aβ production via a PDK1-TACE mechanism and that brain deposition of Aβ induced by Aβ seeds co-transmitted with PrPSc contributes to mortality in prion disease." (PMID 31371707, 2019). "Several previous studies have implicated specific signal transduction pathways in the pathogenesis of prion diseases, including the UPR, oxidative stress, MAPKs, phosphoinositide-dependent kinase-1 (PDK1), metabotropic glutamate receptors, NMDA receptors, and voltage-gated calcium channels." (PMID 30235355, 2018). "Importantly, as the pharmacological inhibition of PDK1 or ROCK reduces motor impairment, lowers brain PrPSc and Aβ levels, and prolongs the lifespan of prion-infected mice, PDK1 and ROCK are currently considered as potential therapeutic targets to combat prion diseases." (PMID 39011540, 2024).
renal cell carcinoma (5 papers, 2012 to 2022). "HIF-1α binds directly to the PDK1 promoter and activates the transcription of PDK1 in human renal cell carcinoma cell lines." (PMID 23050013, 2012).
bladder cancer (4 papers, 2020 to 2023). "Furthermore, we characterized the molecular machinery underlying TNTs formation in bladder cancer and kidney cells and unveiled the crucial role played by RalGPS2, which promotes tunneling nanotubes formation through interaction with Akt and PDK1." (PMID 34944949, 2021).
cholangiocarcinoma (4 papers, 2019 to 2022). A carcinoma that arises from the intrahepatic biliary tree (intrahepatic cholangiocarcinoma) or from the junction, or adjacent to the junction, of the right and left hepatic ducts (hilar cholangiocarcinoma). "Interestingly, SIRT3 inhibits the cholangiocarcinoma progression via inhibiting the “Warburg effect” through the HIF-1α/pyruvate dehydrogenase kinase 1 (PDK1)/PDHA1 downstream signaling pathway." (PMID 35832551, 2022). "SIRT3 down-regulates HIF1α and pyruvate dehydrogenase kinase 1 (PDK1) in cholangiocarcinoma, and suppresses the Warburg effect also by the activation of pyruvate dehydrogenase complex (PDC) and the indirect inhibition of the tumor specific isoenzyme hexokinase II (HK II)." (PMID 32117717, 2020). "SIRT3, downregulated in cholangiocarcinoma (CCA) patients, can prevent tumor progression by inhibiting the HIF1α/PDK1/PDHA1 pathway." (PMID 35136826, 2022).
Diabetic Nephropathy (4 papers, 2020 to 2025). "Among these, CA9 exhibited the largest fold change within the transcriptional regulatory network of HIF1A, while PDK1 was most closely associated with diabetic nephropathy." (PMID 40417738, 2025). "PDK1, a downstream gene of HIF1A, is a critical mediator in diabetic nephropathy, with its downregulation promoting apoptosis in renal podocytes." (PMID 40417738, 2025). "In the present study, we elucidated the novel anti‐diabetic nephropathy mechanism of ZGP and YGP through PPARA and HIF1A transcriptional regulatory networks and their specific downstream genes CA9, PDK1, and PDK4." (PMID 40417738, 2025). "CA9 and PDK1, the downstream genes of HIF1A, and PDK4, the downstream gene of PPARA, were activated by both EZP and EYP, which showed the potential new targets of diabetic nephropathy." (PMID 40417738, 2025).
esophageal squamous cell carcinoma (4 papers, 2012 to 2025). Esophageal squamous cell carcinoma (ESCC) is a type of esophageal carcinoma (EC) that can affect any part of the esophagus, but is usually located in the upper or middle third. "PDK1 is significantly highly expressed in esophageal squamous cell carcinoma compared with adjacent noncancerous tissues and associated with shorter OS." (PMID 34768921, 2021). "GLS enhances glycolysis in esophageal squamous cell carcinoma (ESCC) by interacting with PDK1, so co-targeting GLS and PDK1 may be a novel therapeutic approach for ESCC patients." (PMID 40598593, 2025).
pulmonary fibrosis (4 papers, 2019 to 2025). Chronic progressive interstitial lung disorder characterized by the replacement of the lung tissue by connective tissue, leading to progressive dyspnea, respiratory failure, or right heart failure. "PDK1‐facilitated lactate accumulation has also been implicated in promoting pulmonary fibrosis through the regulation of trans‐differentiation in lung fibroblasts and EMT in alveolar epithelial cells." (PMID 40176272, 2025). "Furthermore, PDK1 has been implicated in the EMT process in pulmonary fibrosis through its role in facilitating lactate accumulation via glycolysis." (PMID 40176272, 2025). "Inhibition of the TGF‐β/HIF‐1α/PDK1 axis via deletion of HIF‐1α expression or targeting PDK1 by drug‐reduced pulmonary fibrosis." (PMID 39417702, 2024). "However, there are also studies indicating that the inhibition of PDK1 significantly attenuated pulmonary fibrosis." (PMID 40417738, 2025).
Renal cyst (4 papers, 2016 to 2024). A fluid filled sac in the kidney. "Given the Wnt11 deficiency dependent changes in the kidney tubular system we also examined possible changes in the genes encoding the “core” PCP pathway and certain other genes (e.g. TCS2, PDK1 and HNF1b) involved in cystic kidney diseases by qRT-PCR using E16.5 and NB kidneys." (PMID 27582005, 2016). "The upregulation of PDK1 (3.3×) and PDK3 (1.5×) in renal cysts suggests the inhibition of PDC activity, and therefore decreased conversion of pyruvate to acetyl-CoA for oxidative metabolism (bottom)." (PMID 39000280, 2024).
retinoblastoma (4 papers, 2017 to 2025). A malignant tumor that originates in the nuclear layer of the retina. "In the current study, we present data to show that PDK1 was overexpressed in human RB tumor specimens, and targeting PDK1 resulted in decreased cell growth and migration in retinoblastoma-derived cell lines." (PMID 28505181, 2017). "In addition, our study showed that inhibition of PDK1 led to increased apoptosis, decreased migration and changes in various metabolic parameters, signifying that inhibition of PDK1 could reverse certain changes associated with retinoblastoma tumor progression." (PMID 28505181, 2017). "In addition, the migration ability of Y79 cells and retinoblastoma patient derived cells was studied by migration assay in response to PDK1 inhibition." (PMID 28505181, 2017). "In retinoblastoma, a combination of DCA treatment led to the inhibition of the PI3K/Akt pathway and reduction in PDK1 protein levels." (PMID 34070873, 2021). "However, the role played by PDK1 is not studied in retinoblastoma (RB)." (PMID 28505181, 2017).
amyloid (3 papers, 2015 to 2019). "In any case, in the absence of effective medicine, further understanding the functional interplay between ROCK and PDK1 may help to design novel therapeutic strategies for amyloid-based neurodegenerative disorders." (PMID 26241960, 2015).
Anxiety (3 papers, 2017 to 2021). Intense feelings of nervousness, tension, or panic often arise in response to interpersonal stresses. "The results evidenced that the double mutation of the PDK1 pleckstrin homology (PH) domain resulted in an enhancement of the negative valence system shown as an increase of responses of fear- and anxiety-like behaviors in anxiogenic situations." (PMID 32457586, 2020). "The anxiety-like phenotypes of 61 mature (11–14-month-old) male and female PDK1 K465E knock-in, heterozygous, and WT mice were studied." (PMID 34203450, 2021). "We recently showed that the double mutation of the PDK1 PH-domain (PDK1−/−) resulted in an enhancement of NVS shown as an increase of responses of fear and anxiety-like behaviors in anxiogenic situations." (PMID 34203450, 2021). "Different PDK1/Akt mutant mice have consistently manifested a higher depressive and/or anxiety-like behavior." (PMID 34203450, 2021). "Hypomorphic PDK1 mice, with a reduced general activity of PDK1, showed several behavioral differences related to anxiety and exploration in various tests." (PMID 32457586, 2020). "The reduced general activity of PDK1 exhibited by the hypomorphic PDK1 mice (PDK1hm) results in several behavioral differences related to anxiety and exploration assessed in various tests, while cognitively unimpaired Akt2 knockout mice (Akt2−/−) presented an anxiety- and depressive-like phenotype." (PMID 32457586, 2020). "However, since there was an increase in open-field activity in PDK1 cKO mice, it cannot be ruled out that increased anxiety may directly cause learning impairment or exacerbate learning deficit in PDK1 mutant mice." (PMID 29104535, 2017). "In the precedent work, we demonstrated that in the PDK1 homozygous mice, anxiety but not working memory was modulated by age with a reduction in its expression at 11–13 months of age." (PMID 34203450, 2021). "Thus, the PDK1/Akt pathway has been reported as intermediating in the role of neurotropic factors, like brain-derived neurotrophic factor (BDNF), in the acquisition of fear and mood disorders like depression and anxiety." (PMID 32457586, 2020).
B Cell lymphoma (3 papers, 2014 to 2025). "CD8+ T cells transduced with PDK1 or PDP1 show compromised protection against mouse B cell lymphoma, which is rescued by glutamine and acetate supplementation." (PMID 40857407, 2025). "We found that PDPK1 (also known as PDK1) was downregulated after POU2F2 knockdown in B Cell lymphoma cells, that could interact with AKT and phosphorylated it at T308." (PMID 33931589, 2021). "To test this, we administered daily glutamine and sodium acetate supplements intraperitoneally to EμMyc B cell lymphoma–bearing mice that received CD8+ T cells transduced with EV, PDK1, or PDP1." (PMID 40857407, 2025). "The phosphorylation of both PDK1 and 4E-BP1 was similarly inhibited by the three-drug combination, suggesting equivalent inhibitory effects of [Gem+Clo+Ed] on the AKT pathway in both T-cell and B-cell lymphoma cell lines." (PMID 24413065, 2014).
cardiomyopathy (3 papers, 2016 to 2024). A disease of the heart muscle or myocardium proper. "For instance, the most cited paper reported that circ-Amotl1, a circular RNA, can physically bind with PDK1 and AKT1, thus promoting the protective nuclear translocation of pAKT, which provides protection against Adriamycin-induced cardiomyopathy." (PMID 38680417, 2024).
colitis (3 papers, 2018 to 2024). Inflammation of the colon. "We finally established a classic of T-cell mediated model colitis in Rag1-deficeint mice, in which a mixture of CD4+CD45RB+CD25- effector T cells plus WT or PDK1-deficient Treg cells was transferred." (PMID 34646383, 2021). "For example, targeting PDK1 with dichloroacetate selectively inhibited the survival, function, and proliferation of Th17 cells and diminished inflammation in models of colitis and EAE." (PMID 29599783, 2018).
colorectal tumors (3 papers, 2016 to 2024). "The Wnt signaling pathway regulates the expression of pyruvate dehydrogenase kinase 1 (PDK1) or lactate transporter MCT-1 (SLC16A1) to promote the proliferation or angiogenesis of colorectal tumors." (PMID 39079386, 2024). "It is known that EGF-R, VEGFR, IGF1R, Src, and PDK1 are overexpressed in human colorectal tumors, so the mechanism of MI-1 antitumour action could consist on inhibition of these kinases in tumor tissue." (PMID 28101521, 2016).
endometrial cancer (3 papers, 2004 to 2022). Primary or metastatic malignant neoplasm involving the endometrium (mucous membrane that lines the endometrial cavity). "API-59CJ-OMe did not affect kinases either upstream of AKT (PDK-1) or in a distinct signal transduction pathway (ERK1/2 and JNK1/2) in endometrial cancer cells." (PMID 15505622, 2004).
esophageal cancer (3 papers, 2014 to 2022). A primary or metastatic malignant neoplasm involving the esophagus. "Another study also verified the tumor-suppressive effect of miR-375 in esophageal cancer cell lines by targeting PDK1." (PMID 25404787, 2014). "Furthermore, knockdown of HCP5 decreased the p-AKT level by miR-216a-3p/PDK1 axis to increase the radiosensitivity of esophageal cancer cells." (PMID 34969363, 2022). "In addition, the role of miR-216a-3p or PDK1 alone in esophageal cancer radiotherapy response is needed to conduct a study." (PMID 34969363, 2022). "Knockdown of HCP5 modulates the miR-216a-3p/PDK1 axis to inhibit AKT activation, eventually improving the radiosensitivity of esophageal cancer." (PMID 34969363, 2022).
gallbladder cancer (3 papers, 2015 to 2021). "In GBM and gall bladder cancer, the PDK1/Jun signaling pathway was shown to promote cell proliferation and the EMT process." (PMID 34768921, 2021). "Here we showed that PDK1 stimulated cell proliferation, invasion and metastasis in gallbladder cancer (GBC), by inducing JunB and epithelial–mesenchymal transition." (PMID 26318166, 2015).
Hypertension (3 papers, 2022 to 2024). The presence of chronic increased pressure in the systemic arterial system. "We previously reported that the deletion of phosphoinositide-dependent kinase-1 (PDK1) in AgRP neurons enhanced SNA, thereby exacerbating hypertension under high-salt feeding conditions." (PMID 35807782, 2022).
hypopharyngeal carcinoma (3 papers, 2016 to 2025). Carcinoma, predominantly squamous cell, arising from the epithelial cells of the hypopharynx. "The in vitro activity of PHT-427 was tested in hypopharynx carcinoma squamous cells (FaDu) to measure the cell viability, PI3KCA/AKT/PDK1 gene expression, and PI3KCA/AKT/PDK1 levels." (PMID 34452203, 2021). "The activation status of the PI3K/AKT/mTOR pathway was investigated in our series of 93 laryngeal and hypopharyngeal carcinomas by analyzing the immunohistochemical expression of multiple upstream and downstream components, such as EGFR, PDK1, PTEN, p-AKT and p-S6." (PMID 27119232, 2016).
ischemic stroke (3 papers, 2022 to 2025). A stroke disorder caused by obstruction of blood flow to the brain, due to thrombotic (local blood clot formation) or embolic (due to a blood clot or other material traveling from another site) event. "As a critical player in platelet-triggered ischemic stroke, PDK1 can increase intracellular Ca2+ in platelets, platelet activation, and aggregability after stimulation with collagen." (PMID 35463086, 2022).
oral cancer (3 papers, 2021 to 2023). "Overall, our work laid the basis for further exploration of the clinical feasibility of targeting PDK1 as a therapeutic molecular target in oral cancer." (PMID 34768921, 2021). "The present data demonstrated that signaling molecules, including PI3K, PDK1, Akt and mTOR, were regulated by ANLN in oral cancer." (PMID 34082790, 2021).
osteoarthritis (3 papers, 2022 to 2026). A noninflammatory degenerative joint disease occurring chiefly in older persons, characterized by degeneration of the articular cartilage, hypertrophy of bone at the margins and changes in the synovial membrane. "Our findings indicated that the inhibition of PDK1 worsens osteoarthritis by mediating the degradation of articular cartilage ECM and inflammation." (PMID 37474941, 2023). "Here, we report the effects of metabolism shift on osteoarthritis and present definitive data that PDK1 activity is one of the major drivers of pathological changes in OA." (PMID 37474941, 2023). "After establishing the DMM-induced osteoarthritis, we showed that the inhibition of PDK1 did promote OA progression by enhancing the expression of MMP13, accelerating the degradation of major ECM structural molecules, and promoting inflammatory responses." (PMID 37474941, 2023). "As a result, osteoarthritis may be exacerbated by enhancing the activity of PDH in articular chondrocytes through the inhibition of PDK1." (PMID 37474941, 2023). "The temporal analysis of gene expression patterns in GSE89408 RNA-seq validation dataset was conducted for the gene expression levels of PDK1, XBP1 and ACACB across different disease stages, including normal, arthralgia, osteoarthritis, undifferentiated arthritis, RA (early), and RA (established)." (PMID 41583523, 2026).
osteoporosis (3 papers, 2019 to 2024). A condition of reduced bone mass, with decreased cortical thickness and a decrease in the number and size of the trabeculae of cancellous bone (but normal chemical composition), resulting in increased fracture incidence. "To confirm the protective effect of PDK1 in vivo, we evaluated the effect of adenovirus-mediated delivery of PDK1 (Ad-PDK1) in a mouse model of glucocorticoid-induced osteoporosis." (PMID 32047474, 2019). "Specific overexpression of PDK1 could be an alternative method to alleviate glucocorticoid-induced osteoporosis." (PMID 32047474, 2019). "Nevertheless, whether PDK1 inhibits osteoblast-induced osteoporosis by regulating glucocorticoid-induced osteoblasts is unclear." (PMID 32047474, 2019).
renal fibrosis (3 papers, 2021 to 2025). A final common manifestation of a wide variety of chronic kidney diseases characterized by glomerulosclerosis and tubulointerstitial fibrosis. "In this study, we found that ZGP, YGP, and its components activated the transcriptional regulatory networks of HIF1A, as well as the downstream genes PDK1 and CA9, which were closely associated with renal fibrosis and ECM degradation." (PMID 40417738, 2025). "ZGP and YGP mediated HIF1A networks and downstream genes of CA9 and PDK1 in TGFβ‐induced HK2 cells for improving renal fibrosis." (PMID 40417738, 2025). "It has been suggested that metabolic reprogramming occurs in renal fibrosis and that pyruvate dehydrogenase kinase 1 (PDK1) plays a crucial role in metabolic reprogramming as an important node between glycolysis and the tricarboxylic acid cycle." (PMID 39518833, 2024).
schizophrenia (3 papers, 2017 to 2024). A major psychotic disorder characterized by abnormalities in the perception or expression of reality. "IPA identified components of ERK and AKT signaling (RAF/MEK/ERK, and PDK1/AKT/GSK3, respectively) as directly interacting with schizophrenia kinases." (PMID 28900113, 2017). "PDK1 is also an interesting gene involved in the PI3K/Akt signaling pathway, which is known to play essential roles during neuronal development, and is related to schizophrenia." (PMID 33276438, 2020).
stomach cancer (3 papers, 2016 to 2021). "Proteomic analysis showed increased PDK1 protein expression in HER2-positive gastric tumours harbouring ERBB-family mutations compared to wildtype tumours." (PMID 33933113, 2021).
acute leukemia (2 papers, 2012 to 2023). A clonal (malignant) hematopoietic disorder with an acute onset, affecting the bone marrow and the peripheral blood. "The highest cytotoxic potential against T-ALL cell lines and patient lymphoblasts was displayed by NVP-BAG956, a dual PI3K/PDK1 inhibitor which has been shown to be effective against BCR-ABL- and mutant FLT3-expressing acute leukemia cells." (PMID 22885370, 2012).